PGBD1 (piggyBac transposable element derived 1)
Description:
Transposase-derived from PiggyBac DNA transposons. Although it has been fully domesticated and lacks transposase activity, PGBD1 has acquired DNA-binding capability. It preferentially binds in and around genes involved in neuronal development, leading to their transcriptional pausing. Notably, PGBD1 suppresses paraspeckle assembly in neuronal cells.
Synonyms: hucep-4; dJ874C20.4; SCAND4
Tractability: PROTAC: UniProt records ubiquitination sites on it; ubiquitination databases record sites on it.
Gene: Protein-coding gene on chromosome 6 (28,281,493 to 28,303,691, forward strand). Ensembl gene ENSG00000137338.
Subcellular location: Nucleus
Subcellular location (Human Protein Atlas): Nucleoplasm; Cytosol
Gene Ontology:
Molecular function: DNA binding; identical protein binding; protein binding; DNA-binding transcription factor activity; sequence-specific DNA binding
Biological process: neurogenesis; regulation of transcription by RNA polymerase II
Cellular component: nucleus; membrane
Genetic constraint (gnomAD): Loss-of-function variants: 25 observed, 34.32 expected, observed/expected ratio (o/e) 0.73, 90% interval 0.53 to 1.02. The upper end of that interval is the gene's LOEUF score, 1.02, which puts it in group 4 of 6, group 1 being the genes least tolerant of losing a copy. Missense variants: 823 observed, 999.25 expected, observed/expected ratio (o/e) 0.82, 90% interval 0.78 to 0.87. Synonymous variants: 291 observed, 354.84 expected, observed/expected ratio (o/e) 0.82, 90% interval 0.74 to 0.9.
Homologues: Orthologues: chimpanzee PGBD1 (99% identical), macaque PGBD1 (95% identical), rabbit PGBD1 (81% identical), pig PGBD1 (81% identical), dog PGBD1 (72% identical), mouse Pgbd1 (33% identical). Paralogues in human: ZSCAN12 (14% identical), ZKSCAN8 (13% identical), ZNF215 (13% identical), ZNF263 (13% identical), ZNF394 (13% identical), ZKSCAN3 (13% identical), ZNF397 (12% identical), ZSCAN30 (12% identical), ZSCAN23 (12% identical), ZSCAN31 (12% identical), ZKSCAN4 (12% identical), ZNF75A (12% identical), and 18 more.
Diseases named in the same sentence as PGBD1 in open-access papers:
PGBD1 is named in the same sentence as 7 diseases in open-access papers, as found by Europe PMC text mining. Sharing a sentence is not in itself a finding about the gene and the disease. The quoted sentences say what the papers report.
mental disorder (2 papers, 2013 to 2026). A disease that has its basis in the disruption of mental process. "Many genetic factors have been shown to play etiological roles in diverse mental disorders, including PGBD1 in schizophrenia and Alzheimer’s disease and TNFα in schizophrenia and bipolar disorder." (PMID 23437227, 2013). "Nine shared genetic loci and six pleiotropic genes, including SCN1A, PGBD1, ZKSCAN3, ZKSCAN4, VRK2, and ZSCAN23, have been identified between epilepsy and psychiatric disorders." (PMID 41733899, 2026).
Alzheimer disease (1 paper, 2013). A progressive, neurodegenerative disease characterized by loss of function and death of nerve cells in several areas of the brain leading to loss of cognitive function such as memory and language. "PGBD1 has been reported to be a susceptibility gene for both schizophrenia and Alzheimer’s disease." (PMID 23437227, 2013).
schizophrenia (1 paper, 2013). A major psychotic disorder characterized by abnormalities in the perception or expression of reality. "Additionally, our earlier two-stage GWAS also found that three single-nucleotide polymorphisms (SNPs; i.e., rs1233710 in ZKSCAN4, rs1635 in NKAPL, and rs2142731 in PGBD1) within this locus had a strong association with schizophrenia in a Chinese Han population." (PMID 23437227, 2013).
PGBD1 also shares sentences with these, for which no sentence is quoted: bipolar disorder (1 paper); COVID-19 (1); epilepsy (1); hemochromatosis (1).